IGF1 (insulin like growth factor 1)
Diseases named in the same sentence as IGF1 in open-access papers (continued):
Sharing a sentence is not in itself a finding about the gene and the disease.
Obesity (continued). "Furthermore, previous research had proved that the high expression of IGF-1 in obesity and DM indicated the increased risk of EOC and poor prognosis." (PMID 28261315, 2017). "Adipocytes were shown to secrete IGF-1, and obesity is associated with increased levels of IGF-1." (PMID 28915700, 2017). "The current study showed 3.9-fold decrease in IGF-1 expression in the diabetic group compared to control group, which may be independently associated with obesity, glucose intolerance, diabetes, and atherogenic dyslipidemia." (PMID 27579151, 2016). "High protein intake has been associated with increased IGF-1 secretion, which may mediate the relation between protein intake and obesity." (PMID 26329684, 2016). "It has been suggested that the mechanism behind the increased risk of obesity associated with high protein intakes during infancy may be the protein-associated stimulation of insulin and IGF-1 release." (PMID 27271662, 2016). "When we compared the EFDs for both the obesity-associated tGSS and IGF1 pathway tGSS, results suggested that there is a stronger association of the IGF1 pathway tGSS's genes with the 70 BC rGSSs than observed for the obesity-associated tGSS's genes with the 70 BC rGSSs." (PMID 26100469, 2015). "However, more recently, IGF-1 deficiency has been associated with an increased prevalence of obesity." (PMID 26467524, 2015). "This seems to suggest that the probable effects of obesity on cancer association could be less specific or directed, when compared to that of the IGF1 signaling pathway." (PMID 26100469, 2015). "The study of the role of IGF1 in cell metabolism has permitted us to associate it with obesity." (PMID 24690978, 2014). "Obesity is also known to be associated with abnormal IGF1 secretion." (PMID 24690978, 2014). "Beside traditional CVD risk factors, obesity is associated with changes in insulin like growth factor-1 (IGF-1) which may be linked to atherosclerosis." (PMID 24616825, 2014). "Obesity is associated with increased free or bioavailable IGF-1." (PMID 25197276, 2014). "However, CRC in the obesity / T2D context involves higher morbidity and mortality risk, due to induced increase in plasma insulin, IGF-1 and adipo/cytokines that promote cell survival, being further increased by treatment with insulin or β-cell secretagogues." (PMID 25375205, 2014). "Included in the effects of obesity is its association with a chronic low-grade state of inflammation as well as elevations in blood glucose and alterations in serum factors such as insulin, leptin, adiponectin, and insulin-like-growth factor (IGF)-1." (PMID 24804677, 2014). "Elevated circulating IGF-1 is an established risk factor for many obesity-associated cancer types." (PMID 23967401, 2013). "Recent epidemiologic studies suggest that IGF-1 is associated with obesity and cancer." (PMID 23405181, 2013). "In addition, recent research has supported a functional role for IGF-1 in obesity associated inflammation and tumorigenesis." (PMID 21696633, 2011). "The chronic systemic inflammation associated with obesity is believed to fuel tumor development and progression, and IGF-1 may mediate obesity-associated inflammation via its effects on immune cells, including macrophages." (PMID 21696633, 2011). "Most circulating IGF1 is produced by the liver, and it is possible that a low BMI is associated with low IGF1 synthesis due to a relatively low supply of nutrients to the liver, whereas obesity is associated with low IGF1 synthesis in the liver due to compromised liver function." (PMID 20472501, 2010). "Low serum IGF1 concentrations in humans were associated with lower visceral but not with lower subcutaneous or total fat mass and IGF1 and blood glucose levels were inversely correlated in obesity before and during energy restriction." (PMID 19689798, 2009).
Obesity (continued). "In addition, disruption in the IGF-1 axis during fetal development, resulting in fetal macrosomia, may create a metabolic predisposition to obesity, which can lead to IR and further increased risk for endocrine disorders." (PMID 40357063, 2025). "Since IGF-1 activity has been implicated in depression, AD and other brain conditions, disruptions in brain activity of this growth factor may explain why loneliness and obesity are risk factors for these different psychiatric disorders." (PMID 41155299, 2025). "Obesity is closely related to PCa aggressiveness and PCa-related mortality; several mechanisms have been suggested to underly this including tumor proliferation via the insulin-like growth factor-1 (IGF-1) pathway and oxidative stress-related inflammatory signaling." (PMID 39280242, 2024). "Consequently, an increasing body of literature proposes an alternative approach using obesity biomarkers, such as circulating hormones (e.g., adipokines, insulin, and insulin-like growth factor [IGF-1]), to delineate obesity phenotypes associated with an elevated risk of morbidity and mortality." (PMID 39822775, 2024). "Moreover, the obesity–cancer association may also be linked to the endogenous hormone metabolism dysfunctions also including insulin, bio-available sex steroids, IGF-1, and IGFBPs." (PMID 38785834, 2024). "In fact, numerous studies of patients with acromegaly have shown that serum levels of GH and insulin-like growth factor-1 (IGF-1) may be associated with the onset and progression of TC, although the influences of age, sex, and other risk factors, such as obesity and stress, remain unclear." (PMID 39104813, 2024). "IGF-1 may play a role in the association between obesity and thyroid cancer." (PMID 36755926, 2023). "Thus, the state of relative GH and IGF-1 deficiency in patients with obesity may have potential implications in the development of NAFLD and NASH." (PMID 36831184, 2023). "The imbalance of IGF-1 in bone tissues caused by aging, obesity, or other factors can result in the onset of the disease osteoporosis; decreased levels of this hormone induced by low protein intake could result in an elevated risk of osteoporosis and bone fracture." (PMID 37892460, 2023). "However, obesity is also associated with GH deficiency, resulting in decreased hepatic GH signaling and decreased hepatic synthesis of IGF1, two factors that may favor the development of steatosis." (PMID 36557260, 2022). "Obesity-associated hyperinsulinemia may play an important role in endometrial cancer through a direct effect via the stimulation of endometrial cell proliferation or indirectly through sex steroid and insulin-like growth factor 1 pathways." (PMID 33799622, 2021). "Obesity is associated with an increased risk of developing several cancers, such as breast cancer, colon cancer, ovarian cancer, endometrial cancer and thyroid cancer and IGF-1 levels are positively associated with the risk of developing breast and prostate cancer." (PMID 31113478, 2019). "Behaviours associated with obesity may also sustain chronic diseases through the induction of pro-inflammatory cytokines and insulin and insulin/IGF-1 resistance—both processes further contributes to the increased production of reactive oxygen species and residual inflammation." (PMID 31426866, 2019). "In line with this, and taking into account that obesity is associated to suppressed GH release, it seems reasonable to propose that other factors (leptin, insulin, adipokines, inflammatory factors, etc.)should contribute to the increased gene expression of GH/IGF-1 axis components." (PMID 25806796, 2015). "In addition, it should be mentioned that higher protein intake in infancy may increase later obesity risk, an effect that may be mediated through insulin and IGF-1." (PMID 25192029, 2014). "A two-step approach integrating IGF-1 and GV improves diagnostic precision and helps to differentiate true GHD from obesity-related GH suppression." (PMID 41749655, 2026).
Obesity (continued). "Our key findings indicate that the exercise‐induced increase in serum total IGF‐1 is blunted in individuals with obesity." (PMID 40574473, 2025). "An increase in leptin, insulin, and IGF-1 and a reduction in ghrelin were established in previous studies of patients affected by OW and I–II stages of obesity." (PMID 39970875, 2025). "Obesity-induced leptin and IGF-1 can activate NF-kB transcription, leading to an increase in cytokines." (PMID 40722609, 2025). "Obesity-induced hyperinsulinemia elevates insulin-like growth factor-1 (IGF-1) levels, which in turn promotes tumour growth and progression." (PMID 41002741, 2025). "Another study demonstrated the role that IGF-1, a hormone elevated in obesity, plays in activating downstream Erk and Akt signaling pathways, showing that upregulation of the pathways via IGF-1 led to the promotion of cancer cell invasion and proliferation." (PMID 40722609, 2025). "We show that humans with obesity exhibit lower circulating levels of total IGF‐1 during endurance exercise." (PMID 40574473, 2025). "Ample evidence indicates that tissue IGF1 resistance is present in both human obesity and animal models of obesity." (PMID 40105689, 2025). "Future research should build on our findings regarding systemic IGF‐1 responses by examining muscle‐specific IGF‐1 expression during and after endurance exercise and its relationship to muscle protein synthesis in humans with obesity." (PMID 40574473, 2025). "Elevated levels of insulin and IGF-1 in obesity create an environment that promotes cell growth and inhibits cell death, accelerating the accumulation of mutations and favoring carcinogenesis." (PMID 41463284, 2025). "The presence of obesity, coupled with metabolic syndrome, can result in hyperinsulinemia and elevated levels of free insulin-like growth factor 1 (IGF-1)." (PMID 40565082, 2025). "SRPK2 mediates SGs formation in obesity‐related pancreatic ductal adenocarcinoma (PDAC) by activating the IGF1/PI3K/mTOR/S6K1 pathway." (PMID 40211955, 2025). "Obesity contributes to the progression of Pca through alteration in the endocrine system, specifically oestrogen and testosterone levels and insulin-like growth factor-1." (PMID 40496310, 2025). "This inflammatory response increases the secretion of proinflammatory cytokines, including tumor necrosis factor (TNF), interleukin-6 (IL-6), and leptin, while levels of insulin-like growth factor-1 (IGF-1) typically decrease with age and obesity." (PMID 41156491, 2025). "The activation of IGF-1 signaling pathways has a significant role in obesity-related gastrointestinal cancer through its effects on cell proliferation, such as on intestinal epithelial cells." (PMID 40722646, 2025). "Elevated BMI prolongs the action of insulin-like growth factor-I (IGF-1) due to sustained high levels of insulin in individuals with obesity." (PMID 40014232, 2025). "Obesity and hyperglycaemia elevate insulin-like growth factor-1 (IGF-1) levels, driving oncogenic pathways such as PI3K/Akt/mTOR, which promote tumour proliferation and survival." (PMID 41002741, 2025). "We show that obesity impairs the exercise‐induced increase in serum total IGF‐1 and IGFBP‐3 concentrations." (PMID 40574473, 2025). "Obesity correlates with decreased levels of albumin, albumin/globulin ratio, IGF-1, and glucose/insulin ratio." (PMID 40901060, 2025). "Our findings demonstrate that CUDC-907 successfully resensitizes tumors to progestin therapy by upregulating PR expression, downregulating the obesity-related factor IGF-1, and inhibiting the PI3K/Akt/mTOR signaling pathway." (PMID 41262902, 2025). "IGF-1 concentrations have been previously reported to increase with age up to puberty during childhood and to be elevated in children with overweight/obesity." (PMID 39899498, 2025).
Obesity (continued). "Obesity induces an aberration of circulating factors (e.g., insulin, growth hormones, IGF-1, androgens, and pro-inflammatory cytokines), which, in addition to reduced physical activity, impact protein synthesis and degradation." (PMID 40610657, 2025). "Insulin-like growth factor 1 (IGF-1) levels were persistently increased (645.48 ± 1.17 ng/mL versus 635.40 ± 1.28 ng/mL; p = 0.011), a result frequently seen in people with significant obesity and preserved GH responsiveness." (PMID 40428329, 2025). "Obesity also facilitates carcinogenesis via insulin/insulin-like growth factor 1 (IGF-1) pathway activation." (PMID 40642165, 2025). "T2DM and obesity are states of hyperinsulinemia, and insulin is known to directly activate IGF1-R on epidermal cells and increase IGF1 levels in the blood, which is the proposed mechanism of action of AN in hyperinsulinemic states." (PMID 39165464, 2024). "IGF-1 stimulates the proliferation of adipocytes, leading to increased fat accumulation and, consequently, higher risks of obesity." (PMID 39599677, 2024). "Congruent with our results reporting substantial number of patients with reduced IGF1 values, previous studies noted both normal and decreased IGF-1 level in patients with obesity." (PMID 39014246, 2024). "Among them, MIP‐1γ, MMP‐3, VEGFR2, IGF‐1, and HGFR are associated with obesity and OPN and OPG are associated with atherosclerotic diseases." (PMID 39001701, 2024). "Obesity promotes the release of insulin-like growth factor-1, proinflammatory cytokines, and the activation of androgen receptors and oxidative stress." (PMID 37940476, 2024). "Insulin/insulin-like growth factor-1 (IGF-1) signaling has been shown to be a critical arbitrator in obesity-related EAC." (PMID 39335147, 2024). "The regulation of this molecule is considerably complex, although it has been established that protein intake is determinantal to IGF-1 levels and obesity is related to decreased levels of IGF-1." (PMID 39451888, 2024). "Obesity-related changes in insulin and bioavailable IGF-1 have been shown to stimulate ovarian androgen synthesis." (PMID 38213908, 2024). "In most cases, the anti-obesity and anti-diabetic properties of these probiotics are mediated by the modulation of the insulin-like signaling pathway (IGF-1)." (PMID 38279322, 2024). "Infants and children with overweight or obesity had significantly lower IGF-1 levels than other BMI categories." (PMID 39438878, 2024). "Obesity induces a variety of systemic changes, including altered levels of insulin, insulin-like growth factor-1 (IGF-1), leptin, adiponectin, steroid hormones, and cytokines, creating an environment that favors tumor initiation and progression." (PMID 39630839, 2024). "This has clinical relevance, as both insulin and free IGF-1 levels are increased in individuals with obesity, and T cells have been found to dominate peripheral inflammation in obesity in human studies, with Th17 cells having a particularly prominent role." (PMID 38383709, 2024). "Different sample sizes, ages, stages of puberty, and definitions used for obesity are among the factors that explain the observed difference in the relationship between serum IGF-1 and BMI." (PMID 39438878, 2024). "Children experiencing overweight or obesity tend to have higher serum levels of insulin-like growth factor 1 (IGF-1) and insulin-like growth factor 2 (IGF-2), specifically during the phase before or at the onset of puberty." (PMID 38612776, 2024). "Among studied infants and prepubertal children, serum IGF-1 was significantly higher in girls than boys and was considerably lower in children with overweight or obesity." (PMID 39438878, 2024). "It is characterized by marked short stature, typical facial features, delayed sexual development, and obesity resulting from the inability to synthesize insulin-like growth factor I (IGF1) in response to growth hormone (GH)." (PMID 38255007, 2024).
Obesity (continued). "By contrast, during puberty, children suffering from obesity exhibited a decline in growth rate, which was correlated with decreases in IGF-1 and testosterone levels in boys and estradiol levels in girls." (PMID 38398863, 2024). "EAC cells can circumvent apoptosis through an obesity-induced IGF1-DAG-PKC-δ pathway, or independently of the PKC-δ pathway via modifications to downstream regulators." (PMID 39395071, 2024). "Children with overweight or obesity had significantly lower IGF-1 than children with other body mass index (BMI) categories." (PMID 39438878, 2024). "One proposed mechanism linking obesity and cancer involves elevated circulating insulin and insulin-like growth factor 1 (IGF-1) levels, which over-activate the IGF system." (PMID 39534224, 2024). "In this study, we investigated the SG effect on the metabolic profile of one hundred Egyptian adult female patients with obesity and the potential role of IGF-1." (PMID 38285303, 2024). "Accordingly, we found that basal IGF-1 was significantly lower in patients with overweight and obesity compared to those with normal weight." (PMID 38902646, 2024). "Nevertheless, the current study results configure the potential clinical utility of MEG3/miR-27a/IGF1/IGFBP3 axis, especially miR-27a in screening and early diagnosis of obesity-associated CRC." (PMID 38704452, 2024). "When we used the ANOVA test among different BMI categories, children with overweight and obesity (4.8%) had significantly lower IGF-1 values than other categories." (PMID 39438878, 2024). "On the other hand, the involvement of obesity in IR prevents IGF-1 from binding to insulin receptors on osteoblasts, leading to dysfunctional insulin signaling, which negatively affects bone remodeling." (PMID 38378872, 2024). "Patients with permanent GHD were also classified according to AACE cutoff for GST based on BMI range for healthy weight (<25 kg/m2), overweight (≥25 kg/m2 and <30 kg/m2), and obesity (≥30 kg/m2) and IGF-1 SDS levels." (PMID 38913686, 2024). "Protein-rich formulas are considered a factor that can accelerate plasma insulin levels and lead to the release of insulin-like growth factor-1, consequently resulting in weight gain and later obesity." (PMID 39759652, 2024). "Despite these limitations, our study provides valuable insights into the role of C-peptide and IGF-1 in the improvement of body composition and physical fitness through exercise intervention in early adolescent boys with obesity." (PMID 39822775, 2024). "Some studies suggest that free IGF-1 increases during obesity and promotes the expression of IGFR (Insulin-like Growth Factor Receptor)." (PMID 38413886, 2024). "Obesity is associated with EAC and abnormalities in insulin-like growth factor-1 (IGF-1) and insulin signaling." (PMID 39335147, 2024). "The correlation of obesity with increased incidences of EAC is supported by a positive correlation of PKC-δ and IGF-1 with obesity in BE and EAC." (PMID 39395071, 2024). "With obesity, the spontaneous and stimulated GH secretion is decreased, but IGF-1 levels are increased, allowing for normal growth in obese children." (PMID 39062266, 2024). "Elevated levels of IGF-1 in obesity and the subsequent dysregulation of downstream signaling pathways have been implicated in cancer progression, particularly in squamous cell carcinoma of the esophagus." (PMID 39395071, 2024). "As a metabolic abnormality, obesity leads to a series of changes in insulin, IGF-1, sex hormones, IGFBPs, and adipokines." (PMID 36755926, 2023). "The impact of obesity on serum IGF-1 levels is a matter of controversy within the scientific community." (PMID 37298507, 2023). "On the other hand, this transcription factor has been found to regulate the expression of obesity-related bioactive molecules (i.e., IL-6, IGF-1, and leptin), further suggesting the potential role of CEBP-β in mediating BC cell/adipocyte crosstalk." (PMID 37447165, 2023).